CDH1 (cadherin 1)
Diseases named in the same sentence as CDH1 in open-access papers (continued):
Sharing a sentence is not in itself a finding about the gene and the disease.
gastric cancer (continued). "Chromoendoscopy facilitated detection of gastric carcinoma foci in CDH1 mutation carriers." (PMID 35499650, 2023). "A recent study found that among patients not exclusively ascertained based on strict HDGC criteria, the cumulative incidence of gastric cancer for individuals with pathogenic CDH1 variants is significantly lower (42% at age 80 years) than what has been previously reported." (PMID 34949788, 2022). "In comparison, 32% of OA patients had stomach cancer, of which 21% carried a CDH1 mutation." (PMID 36433963, 2022). "Moreover, CDH1 mutations are more likely to be detected in areas with a low incidence of gastric cancer." (PMID 34949788, 2022). "Among AYA patients, 53% had stomach cancer, of which 31% carried a CDH1 mutation." (PMID 36433963, 2022). "Thus, higher fraction of the stomach cancer subtype combined with its increased mutation rate led to an overall CDH1 mutation rate twice as high in AYAs as in OAs (19% vs. 9%)." (PMID 36433963, 2022). "pylori infection with an existence of a rare CDH1 mutation could have contributed to this aggressive gastric cancer." (PMID 35877235, 2022). "The prevalence of CDH1 pathogenic variants in patients with gastric cancer and other cancer types is unknown." (PMID 34949788, 2022). "While the level of pT606‐Kaiso was decreased in most gastric cancer samples, the ratio of pT606‐Kaiso to total Kaiso was positively and significantly associated with the amounts of CDH1 (adjusted by GAPDH) in gastric cancer and the paired normal tissue samples from 12 patients." (PMID 35851744, 2022). "Moreover, brain tumors were observed with a higher prevalence in gastric cancer families harboring pathogenic CDH1 germline alterations (4.4%) than in the general population (0.2%)." (PMID 33929593, 2021). "Moreover, a family history of gastric cancer, of Lynch syndrome and of familial adenomatous polyposis, and genetic mutations mainly on the CDH1 gene are strong risk factors known to be associated with hereditary stomach cancer." (PMID 33937056, 2021). "Also, according to the KG, both calcium and rap1 signalling pathways have other gene/protein associations such as ERBB2, KRAS and CDH1, which are further associated with the gastric cancer disease." (PMID 34181736, 2021). "LP/P variants in CDH1 were identified in 6 patients with gastric cancer." (PMID 34251444, 2021). "In addition, sporadic signet-ring cell gastric cancer is reported to be one of the key features of gastric cancer triggered by CDH1 mutation." (PMID 33797633, 2021). "In the present study, it found that the CDH1-160 AA genotype could increase the risk of gastric cancer." (PMID 34422902, 2021). "In addition to these inactivating CDH1 mutation, the occurrence of gastric cancer is related to the polymorphisms of several single nucleic acid glycosides in the CDH1 gene." (PMID 34422902, 2021). "However, application of variant scoring for putative relevance led to a strong reduction of CDH1 variants conferring increased risk of gastric cancer." (PMID 33809393, 2021). "Following the first identification of pathogenic germline variants in the CDH1 gene associated with early-onset diffuse gastric cancer, the International Gastric Cancer Linkage Consortium (IGCLC) has been updating specific guidelines for CDH1 genetic screening of patients and families at risk." (PMID 34503169, 2021). "Based on these findings, we hypothesized that the CDH1 V832M mutation would be prevalent in Korean sporadic gastric cancer patients." (PMID 31892987, 2020). "We investigated whether gastric cancer patients with a CDH1 pathogenic missense mutation, V832M, actually showed characteristics of HDGC; familial gastric cancer, early-onset gastric cancer, and diffuse histology." (PMID 31892987, 2020).
gastric cancer (continued). "However, data on the frequency and clinical characteristics of germline CDH1 mutations in unselected gastric cancer patients are scarce." (PMID 31892987, 2020). "We recently demonstrated that polymorphic variants in AXIN2 and CDH1, which are involved in cell adhesion and migration and are strongly related to breast and gastric cancer, are associated with NSOC, reinforcing the putative link between cancer and oral clefting." (PMID 32143304, 2020). "Overall, this data supports the hypothesis for the pathogenicity of this rare CDH23 variant, as it could play a similar role to that of CDH1 in gastric cancer." (PMID 32276436, 2020). "Loss of expression of E-cadherin in immunohistochemistry may be an indicator for a CDH1-associated gastric cancer." (PMID 32362280, 2020). "Germline mutation in CDH1 (E-cadherin) is widely detected in gastric cancer." (PMID 32695120, 2020). "About 10–20% of gastric cancer is caused by heredity with confirmed causes in 1–3%, predominantly linked to the hereditary diffuse gastric cancer caused by pathogenic variants in the CDH1 gene." (PMID 32321466, 2020). "Notably, all 15 gastric cancer cases that were diagnosed as a result of interventions available to known CDH1 mutation carriers were diagnosed with early-stage disease and were still alive five years post diagnosis (data not shown)." (PMID 29589180, 2019). "Here, the authors perform whole-genome sequencing on 168 gastric cancer patients and identified tandem-duplications of super-enhancer ZFP36L2 in 10% of gastric cancer, and mutational signatures in tumors with cadherin 1 mutations that associated with poor prognoses." (PMID 31048690, 2019). "Over the past 2 decades, approximately 160 CDH1 germline variants have been published; the majority were described in probands with strong family history of cancer and from countries with a low-incidence rate of stomach cancer." (PMID 30895400, 2019). "The contribution of CDH1 germline variants to gastric cancer burden among young adults is unknown in Brazil." (PMID 30895400, 2019). "Early broad pharmacologic screens in in vitro models of diffuse gastric cancer indicate that dysregulated EGFR receptor and downstream effector signaling may be involved in aberrant signal transduction selective for CDH1-deficient gastric cancer cells." (PMID 29468433, 2018). "Germline mutations, specifically in the CDH1 gene, associated with gastric cancer diagnosis at a younger age and with a diffuse phenotype might have contributed to this disproportion." (PMID 30281703, 2018). "The same is true regarding CDH1, associated with lobular BC and gastric cancer." (PMID 30257646, 2018). "Our group conducted a differential high-throughput drug screen in gastric cancer cells derived from a stage IV HDGC patient with a truncating c.1380delA CDH1 germline mutation and gastric cancer cells derived from a liver lesion of a gastric cancer patient with wild type CDH1." (PMID 29468433, 2018). "In addition to having an increased risk of gastric cancer, CDH1 mutation carriers also have an increased risk of lobular breast carcinoma." (PMID 30568591, 2018). "Upon additional drug response testing, dual PI3K (Phosphatidylinositol 3-Kinase)/mTOR and topoisomerase 2A inhibitors displayed up to >100-fold increased activity in hereditary c.1380delA CDH1 gastric cancer cells inducing apoptosis most effectively in cells with deficient CDH1 function." (PMID 28460635, 2017). "To compare the loss of CDH1 due to germline mutations in gastric cancer cells derived from a HDGC patient to sporadic gastric cancer cells, we performed genome-wide microarray profiling in c.1380delA CDH1 SB.mhdgc-1 and 7 sporadic gastric cancer cell lines using the Illumina HumanHT-12 v4 platform." (PMID 28460635, 2017).
gastric cancer (continued). "The mutations described in this paper demonstrate the existence of gastric cancer casescaused by CDH1 germline mutations in an endemic region of gastriccancer (northern Brazil), and such information is frequently ignored due to thesignificant number of environmental factors present." (PMID 27192129, 2016). "In the West, hereditary gastric cancer was first related to the CDH1 mutation." (PMID 27127881, 2016). "To investigate whether this CDH1 variant segregates with gastric cancer in the family, we obtained CDH1 testing results of the 63 year old brother (tested in a reference lab) which indicates he carries the CDH1 c." (PMID 27880784, 2016). "Readers should be reminded here that CDH1 was initially known as a susceptibility gene for gastric cancer of the diffuse type, following the identification of germline mutations in Caucasian, Maori and African-American families with multiple affected individuals." (PMID 25848941, 2015). "Therefore, we investigated the influence of the CDH1 − 160C → A promoter polymorphism and haplotypes on risk for diffuse and intestinal gastric cancer separately by direct sequencing." (PMID 24684952, 2014). "In fact, one of the first steps in the metastatic cascade is the loss or downregulation of E-cadherin expression or function by cancer cells, and it is known that mutations of its codifying gene (CDH1) increases the risk to develop particular types of breast and gastric cancers." (PMID 24553076, 2014). "Besides gastric cancer, splice site mutations of CDH1 were also revealed in colorectal cancer and breast cancer." (PMID 25184143, 2014). "It has been suggested that CDH1 may contribute to gastric cancer risk in a complex manner due to multiple polymorphic variants." (PMID 24684952, 2014). "The TCGA gastric cancer data also show a high frequency of somatic CDH1 mutations." (PMID 25315765, 2014). "Therefore, we conducted a case–control study to investigate the association of the CDH1 − 160C → A promoter polymorphism and haplotypes for cancer risk related to sporadic diffuse and intestinal gastric cancer by direct sequencing analysis." (PMID 24684952, 2014). "Her family history was significant for a sister with metastatic gastric adenocarcinoma (deceased at age 41), two aunts and one cousin with gastric carcinoma (diagnosed in 40s, two of which are deceased), and a brother and niece identified as CDH1 mutation carriers." (PMID 23849133, 2013). "The most important GC susceptibility gene is CDH1, which accounts for 1-3% of gastric cancers." (PMID 23231819, 2012). "However, considering the rarity of the syndrome, CDH1 mutations make a small contribution to the total burden of familial gastric cancer." (PMID 19888225, 2010). "Among the genetic factors, the CDH1 gene, alternatively referred to as the E-cadherin gene, is one of the most important tumor suppressor genes in gastric cancer, and mutations, chromosomal deletions, and epigenetic modifications have been reported as mechanisms that cause CDH1 inactivation." (PMID 19671196, 2009). "The purpose of this study was to evaluate if germline promoter hypermethylation of the tumor suppressor gene CDH1 (E-cadherin) might cause predisposition to gastric cancer." (PMID 19671196, 2009). "This is the first report of an investigation into whether germline mono-allelic hypermethylation of the CDH1 promoter is a predisposing factor for gastric cancer." (PMID 19671196, 2009). "Gastric cancer peritoneal metastasis (GCPM) typically indicates a poor clinical prognosis and is frequently observed in diffuse gastric cancer (GC) patients with CDH1 loss of function." (PMID 40299206, 2025).
gastric cancer (continued). "Furthermore, the clinical implications of CDH1 mutations extend beyond gastric cancer." (PMID 40585607, 2025). "Moreover, dietary factors may also interact with CDH1 mutations and H. pylori infection to influence gastric cancer risk." (PMID 40585607, 2025). "As we know, germline mutations in the tumor suppressor gene CDH1 could lead to hereditary diffuse gastric cancer (HDGC), our finding about somatic mutations of CDH1 in GLP further emphasizes the importance of the CDH1 mutations in certain subtypes of gastric cancer." (PMID 36450891, 2023). "On the other hand, hereditary risk factors involve mostly alteration of the cadherin 1 gene (CDH1), which is associated with diffused gastric cancer cases; this genetic disorder is inherited in an autosomal dominant manner and represent 1–3% of GC cases [1,]." (PMID 37609398, 2023). "Furthermore, the variant type of CDH1 in this family might be related the delayed onset of gastric cancer." (PMID 36719602, 2023). "Hereditary diffuse gastric cancer (HDGC) is one of the most common forms of GC, which is associated with familial history, caused by mutations in the cadherin 1 (CDH1) gene." (PMID 35586683, 2022). "Hereditary diffuse gastric cancer (hDGC) is the most recognized familial GC, caused by germline mutations in genes: CDH1 and, rarely, in CTNNA1." (PMID 35163157, 2022). "In gastric cancer (GC), mutation and/or downregulation of CDH1/Cadherin-1 is recurrent in sporadic and hereditary diffuse GC type." (PMID 36556227, 2022). "Notably, five probands with CDH1 P/LP variants had concomitant gastric cancer and CRC." (PMID 34949788, 2022). "Therefore, CDH1 mutations/expression may represent a diagnostic or prognostic marker of gastric cancer." (PMID 36317124, 2022). "CDH1 is the main gene involved in hereditary GC, encoding the E-cadherin protein, whose germline mutations are responsible for Hereditary Diffuse Gastric Cancer (HDGC)." (PMID 35912206, 2022). "However, the study of somatic CDH1 mutations and early-onset gastric cancer was little." (PMID 35498538, 2022). "Mutations in the CDH1 gene have been disclosed in 33 of 395 (8.4%) cases of GC (according to the TCGA Firehose Legacy study) and are a more frequent event in the diffuse gastric cancer (DGC) subtype (20.8% of cases, TCGA Firehose legacy study)." (PMID 36556227, 2022). "Finally, we found an inverse correlation between E-cadherin and Integrin β1 expression in a series of 262 gastric carcinoma cases, confirming that E-cadherin loss triggers deregulation of cell-matrix interactions regardless of the mechanism leading to CDH1 inactivation." (PMID 34486077, 2022). "To date, we do not know if asymptomatic individuals in these families will develop gastric cancer later, the cumulative risk of developing GC in these women or their relatives with CDH1 mutations is unknown; it is possible that in this contest the penetrance risk for GC is lower or absent." (PMID 34066044, 2021). "E-cadherin is a key player in gastric cancer (GC) and germline alterations of CDH1, its encoding gene, are responsible for Hereditary Diffuse Gastric Cancer (HDGC) syndrome." (PMID 34066170, 2021). "Hereditary diffuse gastric cancer (HDGC) is the most recognizable familial GC, which is caused by cadherin 1 gene (CDH1) alterations." (PMID 32512697, 2020). "Of note, germline mutations in the CDH1 gene have been identified in familial clusters of GC, particularly in hereditary diffuse gastric cancer (HDGC) syndrome." (PMID 32987716, 2020). "However, a combined analysis of 264 sporadic early age onset gastric cancer (EOGC) cases from low-incidence countries found that 2.3% of the subjects had a CDH1 germline pathogenic mutation, highlighting the importance to investigate hereditary cancer in this subpopulation." (PMID 30895400, 2019). "Therefore, AKT may represent an attractive drug target for gastric cancers with inactivating CDH1 mutations." (PMID 31540244, 2019).
gastric cancer (continued). "The main gene involved in gastric cancer (GC) predisposition is CDH1, the pathogenic variants of which are associated with diffuse-type gastric cancer (DGC) and lobular breast cancer (LBC)." (PMID 31514334, 2019). "With the exclusion of the rare (<1% of GC) hereditary diffuse gastric cancer (HDGC) condition harboring a CDH1 gene mutation, the observed familial clustering of GC cannot, to date, be explain only on genetic bases." (PMID 29518896, 2018). "In addition to increasing the risk of gastric cancer, CDH1 germline mutations also increase the risk of invasive lobular carcinoma of the breast, and possibly colorectal adenocarcinoma, and are associated with blepharocheilodontic syndrome (a congenital development disorder)." (PMID 30568591, 2018). "The CDH1 gene, coding for the E-cadherin protein, is linked to gastric cancer (GC) susceptibility and tumor invasion." (PMID 29295527, 2017). "However, different incidence rates of gastric cancer were observed under the same personal and environment conditions, suggesting that low-penetrance genes other than CDH1 might play a role in gastric cancer susceptibility." (PMID 27127881, 2016). "Additionally, the instability of CDH1 transcripts with germline truncating mutations such as those resulting in premature termination codons, are subject to nonsense-mediated decay, which has been correlated with earlier age of onset of gastric cancer." (PMID 27880784, 2016). "Loss of CDH1/E-cadherin expression and increased cancer stem cell self-renewal are processes that often take place when gastric cancer (GC) is developing." (PMID 27721458, 2016). "Besides CDH1, few hereditary gastric cancer predisposition genes have been previously reported." (PMID 26506520, 2015). "The patient carrying the CDH1 mutation had infiltrating ductal carcinoma of the breast, and her two blood relatives in the same lineage were diagnosed with gastric cancer; however, the histological types of the two gastric cancers were unknown." (PMID 25927356, 2015). "Hence, evaluation of expression of E-cadherin or alterations in its encoded CDH1 gene may provide promising applications for diagnosis, prognosis, or therapeutic targets for gastric cancer." (PMID 25184143, 2014). "Mutations in CDH1 are the genetic cause of up to 48% of the diffusion gastric cancer kindreds, while in contrast to other cancer predisposition syndromes, splice-site and missense mutations are common, suggesting that even reduced E-cadherin expression can be deleterious." (PMID 23586058, 2013). "Mismatch repair (MMR) and germline E-cadherin (CDH1) mutations are two of the major pathways of carcinogenesis in familial gastric cancer (GC)." (PMID 23555086, 2013). "Additionally, environmental and lifestyle factors, including dietary habits, smoking, alcohol consumption, and other lifestyle elements, may influence gastric cancer risk and potentially confound or obscure the relationship between CDH1-160C>A polymorphism and gastric cancer susceptibility." (PMID 40416864, 2025). "CDH1 mutations are associated with HDGC, which carries a high risk of developing gastric cancer, with penetrance estimates ranging from 50% to 80%, depending on various factors such as gender and ethnicity." (PMID 40585607, 2025). "The potential role of immunotherapy in CDH1-related gastric cancer, particularly HDGC, is an emerging area of research that is gaining attention due to the unique molecular characteristics associated with CDH1 mutations." (PMID 40585607, 2025). "For instance, users can select CDH1 to visualize its spatial localization within gastric cancer tissue using UMAP and tissue heatmaps." (PMID 41300276, 2025). "While CDH1 mutations are central to HDGC, a broader spectrum of genetic variations contributes to gastric cancer susceptibility." (PMID 40585607, 2025).